SCP2D1-AS1 (SCP2D1 antisense RNA 1)
Synonyms: dJ1068E13.1; formerly C20orf78
Gene: Long non-coding RNA gene on chromosome 20 (18,799,554 to 18,830,209, reverse strand). Ensembl gene ENSG00000149443.
Diseases named in the same sentence as SCP2D1-AS1 in open-access papers:
SCP2D1-AS1 is named in the same sentence as 1 disease in open-access papers, as found by Europe PMC text mining. Sharing a sentence is not in itself a finding about the gene and the disease.
SCP2D1-AS1 shares sentences with these, for which no sentence is quoted: neurodegenerative disease (1 paper).